CYP1A1 (cytochrome P450 family 1 subfamily A member 1)
Diseases named in the same sentence as CYP1A1 in open-access papers (continued):
Sharing a sentence is not in itself a finding about the gene and the disease.
leiomyoma (1 paper, 2014). A well-circumscribed benign smooth muscle neoplasm characterized by the presence of spindle cells with cigar-shaped nuclei, interlacing fascicles, and a whorled pattern. "In parallel, in another mutuallyexclusive pathway 16α-hydroxylation producesmetabolites with strong estrogenic properties.Polymorphisms in CYP1A1 may affect the activityof the produced enzyme and contribute to the etiologyof leiomyoma." (PMID 24567938, 2014).
liver dysfunction (1 paper, 2013). "Since ethical constraints do not permit methodologically rigorous studies in humans, this question was addressed by investigating the effect of the prototypical inducer benzo[a]pyrene (BP) on CYP1A1 and CYP1A2 in cirrhotic rats stratified according to the severity of liver dysfunction." (PMID 23626760, 2013).
liver failure (1 paper, 2021). A liver disease characterized by the liver losing or has lost all of its function. "The reported pharmacokinetic study suggested that CYP2E1 was the most stable enzyme, whereas CYP2C19 (with CYP1A1 and CYP2D6 in the middle) was the most vulnerable in liver failure." (PMID 34575411, 2021).
mycotoxicosis (1 paper, 2025). Poisoning caused by the ingestion of mycotoxins (toxins of fungal origin). "In the present study, low-dose ZEN mycotoxicosis induced specific changes in CYP1A1 mRNA expression in both parts of the colon." (PMID 40711168, 2025).
nodular goiter (1 paper, 2011). Goiter characterized by discrete tissue mass(es) that may or may not produce thyroid hormones. "The methylation rate of these genes, except for CYP1A1, was higher in normal thyroid tissues than nodular goiter tissues." (PMID 21988780, 2011).
non-Hodgkin lymphoma (1 paper, 2020). Distinct from Hodgkin lymphoma both morphologically and biologically, non-Hodgkin lymphoma (NHL) is characterized by the absence of Reed-Sternberg cells, can occur at any age, and usually presents as a localized or generalized lymphadenopathy associated with fever and weight loss. "In this sense, epigenetic deregulation of CYP1A1 could be of interest since genetic polymorphisms in CYP1A1 gene have been related to a higher risk of non-Hodgkin lymphoma." (PMID 33333886, 2020).
Nystagmus (1 paper, 2020). Rhythmic, involuntary oscillations of one or both eyes related to abnormality in fixation, conjugate gaze, or vestibular mechanisms. "The fact that two proteins, CYP1A1 and TiPARP, are not induced in the heterozygous patients who lack the Nystagmus phenotype, indicate that these genes are not involved disease development." (PMID 33193710, 2020). "The fact that CYP1A1 and TiPARP genes are not induced upon BA-activation of AHR in the heterozygotes, who do not exhibit the nystagmus phenotype, might suggest that their gene products are not involved in the ocular pathology observed in the homozygous patients." (PMID 33193710, 2020).
oral cavity tumors (1 paper, 2008). "The limitednumber of subjects with mutant CYP1A1 alleles did not allow for a calculationof the OR for oral cavity tumors." (PMID 19259333, 2008).
Oral leukoplakia (1 paper, 2018). A thickened white patch on the oral mucosa that cannot be rubbed off. "Xenobiotic metabolizing enzymes CYP1A1 and CYP1B1 were observed also in a cellular model of oral leukoplakia." (PMID 30041465, 2018).
ovarian tumor (1 paper, 2020). "Preclinically, the antitumor benzothiazoles 5F 203 and Phortress evoked potent antiproliferative activity in breast and ovarian tumor models, inducing CYP1A1 expression and generating DNA adducts, which are converted to lethal strand breaks in sensitive cell lines and xenografts only." (PMID 32443455, 2020). "In addition to CYP1A1 induction and AhR nuclear translocation, other markers of sensitivity to 5F 203 have been identified in ovarian tumors." (PMID 32443455, 2020).
parasitic infections (1 paper, 2023). "This significant up-regulation in cyp1a1, il-1ß, and tnf-α expression might contribute to proinflammatory and inflammatory responses due to bacterial and parasitic infections." (PMID 38104092, 2023).
phimosis (1 paper, 2018). A condition in which there is constriction in the tip of the foreskin resulting in inability to fully retract the foreskin over the glans penis. "Negative correlations were found between the methylation level of SRD5A2, especially at the − 221 Sp1 site, and the CYP1 family mRNA expression levels (CYP1A1, p = 0.002; CYP1B1, p = 0.007) in hypospadias patients, but not in phimosis patients." (PMID 29080015, 2018).
polycystic ovarian syndrome (1 paper, 2025). "A study conducted among Egyptian women has highlighted the potential influence of CYP1A1 gene polymorphism (6235T < C) on hormonal profiles and folliculogenesis, potentially contributing to an increased susceptibility to polycystic ovarian syndrome." (PMID 39910959, 2025).
polycythemia vera (1 paper, 2025). "In the Jordanian population, the GSTM1 null genotype alone and in combination with the CYP1A1 m1 genotype may be predisposing risk factors for polycythemia vera." (PMID 40357364, 2025).
postmenopausal osteoporosis (1 paper, 2025). Metabolic disorder associated with fractures of the femoral neck, vertebrae, and distal forearm. "Moreover, polymorphisms in estrogen metabolism-related genes, such as PDSS1, CYP19A1, CYP1A1, and CYP1B1, have been associated with varied efficacy of raloxifene, a selective estrogen receptor modulator frequently prescribed for postmenopausal osteoporosis." (PMID 40411668, 2025).
psychological distress (1 paper, 2016). "Data analysis with two way ANOVA shows that psychological distress, CYP1A1*4 and CYP1A1*2C polymorphisms significantly affect but do not interact among them to influence sperm parameters." (PMID 27220890, 2016). "The present study was designed to assess the effect of psychological distress and CYP1A1 polymorphisms and their interactions on parameters of seminal analysis." (PMID 27220890, 2016).
pulmonary fibrosis (1 paper, 2023). Chronic progressive interstitial lung disorder characterized by the replacement of the lung tissue by connective tissue, leading to progressive dyspnea, respiratory failure, or right heart failure. "Genetic polymorphisms in SNPs related to ROS metabolism, such as cytochrome P450 Family 1 subfamily A Member 1 (CYP1A1) and cytochrome P450 Family 1 subfamily B Member 1 (CYP1B1), as well as antioxidant enzymes, such as GST and SOD, increase susceptibility to CS-induced pulmonary fibrosis." (PMID 37371940, 2023).
small cell lung carcinoma (1 paper, 2009). Small cell lung cancer (SCLC) is a highly aggressive malignant neoplasm, accounting for 10-15% of lung cancer cases, characterized byrapid growth, and early metastasis. "In addition, the expression of CYP1A1 and AhR in small-cell lung carcinoma has been proposed as a putative diagnostic marker and has also been correlated with a history of cigarette smoking." (PMID 19531241, 2009).
small intestine cancer (1 paper, 2015). A primary or metastatic malignant neoplasm involving the small intestine. "The expression levels of CYP1A1 are positively linked with various malignancies, such as breast, esophageal and smoking-related lung and small intestine cancer." (PMID 26580399, 2015).
systemic sclerosis (1 paper, 2023). A chronic disorder, possibly autoimmune, marked by excessive production of collagen which results in hardening and thickening of body tissues. "Highly significant DEGs including CYP1A1 and AGTR2 might be associated with systemic sclerosis." (PMID 38137330, 2023).
type 2 diabetes (1 paper, 2020). "Coffee consumption, mainly driven by SNPs in the CYP1A1/2 and AHR genes which are also associated with higher caffeine intake but lower blood caffeine metabolites, was positively associated with type 2 diabetes in the inverse-variance weighted and weighted median models." (PMID 32895727, 2020).
Urinary incontinence (1 paper, 2024). Loss of the ability to control the urinary bladder leading to involuntary urination. "However, in our study, the use of quercetin did not benefit the case AU, who had slow genotypes in CYP1A1 rs1048943-TT, COMT rs4680 -AA, rs4633-TT and MAO rs6323-TT, and urinary incontinence was observed after quercetin use." (PMID 39148948, 2024).
vascular ectasia (1 paper, 2018). "For example, nodes such as CYP1A1, CYP1A2, CYP1B1 in module 1 belonged to cytochrome P450 (CYPs) family, which could enrich in epoxygenase P450 pathway and relate with cardiovascular-related functions such as vascular ectasia." (PMID 30158870, 2018).
Wilson disease (1 paper, 2021). A very rare inherited multisystemic disease presenting non-specific neurological, hepatic, psychiatric or osseo-muscular manifestations due to excessive copper deposition in the body. "Gene expression of analyzed enzymes ranged between 18 and 65% compared to control group and significantly lower protein content of CYP1A1, CYP1A2, CYP2C8, CYP2C9, CYP3A4 and CYP3A5 enzymes was observed in Wilson’s disease." (PMID 34117631, 2021).
cancer (186 papers, 2002 to 2026). A tumor composed of atypical neoplastic, often pleomorphic cells that invade other tissues. "For MspI polymorphisms, the overall pooled analysis revealed a significant association with cancer risk in the Brazilian ethnic group (2.46 [95% CI: 0.00; 305699178.1]) with moderate heterogeneity observed within the genetic models of CYP1A1 polymorphisms." (PMID 41369042, 2025). "The results of this meta-analysis indicate that the understanding of CYP1A1 polymorphisms is necessary to determine the etiology of cancer." (PMID 41369042, 2025). "The significant association among CYP1A1 polymorphisms and cancer can further be studied by selecting studies focused on a particular cancer type and containing a large sample size within a specific ethnic population." (PMID 41369042, 2025). "LSVH with the CYP1A1 Msp1 rs4646903 risk (GG) genotype had a 2-fold increased risk of younger age at cancer diagnosis than those with the wild-type (AA) genotype (Adj HR: 2.03 [1.01–4.08], p = 0.034)." (PMID 39457514, 2024). "AHR activated a specific gene, CYP1A1, which caused many oncogenic genes to combine with DNA to form cancer-promoting combinations, thus promoting the development of cancer." (PMID 39691708, 2024). "RC reduced 5-mC and 5-hmC; HTPs altered CpG, affecting CYP1A1 mRNA and methylation, linked to cancer risk." (PMID 39440184, 2024). "Our findings align with previous studies suggesting that the CYP1A1 rs4646903 SNP elevates the risk of younger age at cancer diagnosis in LSVH." (PMID 39457514, 2024). "Evidence shows that polymorphic CYP450s genes variants are associated with predisposition to such serious diseases as malignant neoplasms (MNs), for example rs1048943 in the CYP1A1 gene." (PMID 36553620, 2022). "The polymorphisms of CYP1A1 were found to be strongly associated with susceptibility to various cancers." (PMID 32457635, 2020). "To date, genetic polymorphisms of human CYP1A1 have been widely studied for the susceptibility to various cancers (e.g., cancer of lung, oral, larynx, breast, thyroid, prostate, renal, cervix uteri, gastric, and colon)." (PMID 31983191, 2020). "At present, only a few studies have reported an association between CYP1A1 haplotypes and cancer susceptibility." (PMID 31983191, 2020). "The aim of this study was to evaluate any association between CYP1A1 (T6235C and C4887A, A4889G) gene polymorphisms and the risk of oral pre-cancer and cancer." (PMID 30803192, 2019). "A transition from T to C in the 3’UTRof CYP1A1 gene results in the introduction of an MspI restriction site and is associated with increase in enzyme activity and hence cancer risk." (PMID 30803192, 2019). "These genetic variants of CYP1A1 genes, besides causing enhanced enzyme activity, are also known to play a major role in the pathogenesis of several cancers." (PMID 30803192, 2019). "Here, we performed enzymatic assays using several isoforms of CYP 450 as CYP1A1, 2E1 and 3A4 which are involved in the metabolism of chemical carcinogens that have been associated with several cancer." (PMID 31798678, 2019). "In the present study, 250 patients with oral pre-cancer and/or cancer and 250 healthy controls were genotyped for CYP1A1 T6235C, C4887A and A4889G polymorphisms by the PCR-RFLP method." (PMID 30803192, 2019). "Variants CYP1A1*2A, CYP1A1*2C, CYP1A1*3 and CYP1A1*4 with trivial names m1, m2, m3 and m4; respectively were the most commonly studied for cancer link." (PMID 28074113, 2017). "Inaddition, such studies will help identify pathophysiological factors that lead toaltered CYP1A1/1B1 expression and increased cancer risk, thus providing usefulinformation for the prevention of female genital and colorectal cancers." (PMID 29276805, 2016). "Understanding the nuclearreceptor mediated regulation of CYP1A1 and 1B1 expression in these tissues isnecessary for identifying cancer risk factors and developing CYP1A1/1B1-targetedanti-cancer therapeutics." (PMID 29276805, 2016).
cancer (continued). "The genetic polymorphisms of CYP1A1/1B1,which lead to altered metabolic activity, are associated with the risk of cancer orother premalignant diseases in the human uterus, cervix, vagina and colorectaltissue." (PMID 29276805, 2016). "Polymorphisms in genes encoding the drug metabolizingenzyme CYP1A1 contribute to the variabilityin susceptibility to various cancers." (PMID 26464823, 2015). "Agundez revealed an association between CYP1A1 enzyme activity and the risk of developing several types of cancers, including EC." (PMID 25886559, 2015). "Unfortunately, many pharmaceutical companies have excluded development of AhR ligands from their pipelines due to concerns that CYP1A1 induction will increase cancer risk or otherwise induce “TCDD-like toxicity”." (PMID 24586378, 2014). "Overall, a significant elevated risk of cancer was associated with CYP1A1 MspI and Ile462Val polymorphisms for all genetic models studied." (PMID 24391993, 2013). "In the past twenty years, many molecular epidemiological studies have been conducted to investigate the association between CYP1A1 polymorphisms and cancer risk in humans." (PMID 24391993, 2013). "In conclusion, although significant heterogeneity from included studies existed, our meta-analysis provided evidence to support an association between the CYP1A1 MspI and Ile462Val polymorphisms and increased cancer risk." (PMID 24391993, 2013). "The results of this meta-analysis suggest that CYP1A1 MspI and Ile462Val polymorphisms contribute to increased cancer susceptibility among Asians." (PMID 24391993, 2013). "The effects of the two genotypes of each CYP1A1 polymorphism are diverse according to subgroup analysis stratified by ethnicity, cancer type, and source of control." (PMID 24391993, 2013). "The risk of cancers is frequently higher in individuals with combined mutant genotypes of CYP1A1*2A and GSTM1 null genotype than in those with CYP1A1 or GSTM1 gene alone." (PMID 24151610, 2013). "It is noteworthy that all studies on the relationship between CYP1A1 genotype and cancer have focused on each polymorphism separately." (PMID 24151610, 2013). "To date, many studies have examined the association between CYP1A1 MspI and Ile462Val polymorphisms and cancer risk in various populations, but their results have been conflicting rather than consistent." (PMID 24391993, 2013). "The relations of CYP1A1 Ile462Val variations with cancer risk have been evaluated by several meta-analyses." (PMID 23056546, 2012). "A commonly studied single nucleotide polymorphism (SNP) in the CYP1A1 gene has been indicated to associate with cancer susceptibility." (PMID 22846179, 2012). "Previously, several meta-analyses have been devoted to the association of CYP1A1 MspI polymorphism with other cancer risk." (PMID 22846179, 2012). "A thymine/cytosine point mutation in the MSP I restriction site of cytochrome P450 1A1 (CYP1A1) has been linked to susceptibility to smoking-related cancers and is reported to result in increased enzyme activity." (PMID 22876118, 2012). "CYP1A1 is a member of the CYP1 family of cytochrome P450 implicated in cancer cell response to therapeutic agents." (PMID 23071625, 2012). "CYP1A1 is found in lungs, lymphocytes, placenta, and skin with low constitutive expression in liver and has been implicated in cancers caused by polycyclic aromatic hydrocarbons (PAHs)." (PMID 22864238, 2012). "A commonly investigated single nucleotide polymorphism (SNP) in the CYP1A1 gene has been suggested to have a correlation with cancer risk." (PMID 23056546, 2012). "Available evidence suggests at least a secondary role of the CYP1A1 polymorphisms for increased risks of smoking-related cancers although the association between these polymorphisms and enzyme activity or property remains controversial." (PMID 20534171, 2010).